SAXO2 (stabilizer of axonemal microtubules 2)
Synonyms: FAM154B; DKFZp666G057
Tractability: No criterion of Open Targets' tractability assessment is met for any kind of drug.
Gene: Protein-coding gene on chromosome 15 (82,262,810 to 82,284,930, forward strand). Ensembl gene ENSG00000188659.
Subcellular location (Human Protein Atlas): Centrosome; Connecting piece; Cytosol; Mid piece
Gene Ontology:
Molecular function: protein binding; microtubule binding
Cellular component: axonemal microtubule; centriole; ciliary basal body; cytoskeleton; sperm flagellum
Genetic constraint (gnomAD): Loss-of-function variants: 19 observed, 19.23 expected, observed/expected ratio (o/e) 0.99, 90% interval 0.69 to 1.45. The upper end of that interval is the gene's LOEUF score, 1.45, which puts it in group 5 of 6, group 1 being the genes least tolerant of losing a copy. Missense variants: 455 observed, 512.72 expected, observed/expected ratio (o/e) 0.89, 90% interval 0.82 to 0.96. Synonymous variants: 150 observed, 168.94 expected, observed/expected ratio (o/e) 0.89, 90% interval 0.78 to 1.02.
Homologues: Orthologues: pig SAXO2 (85% identical), chimpanzee SAXO2 (85% identical), dog SAXO2 (84% identical), rat Saxo2 (80% identical), mouse Saxo2 (72% identical), guinea pig SAXO2 (71% identical), macaque SAXO2 (65% identical), tropical clawed frog saxo2 (59% identical), zebrafish saxo2 (45% identical), Caenorhabditis elegans T08G11.3 (22% identical), Caenorhabditis elegans H03A11.2 (22% identical), Drosophila melanogaster CG7131 (21% identical), and 1 more. Paralogues in human: SAXO1 (34% identical).
Diseases named in the same sentence as SAXO2 in open-access papers:
SAXO2 is named in the same sentence as 3 diseases in open-access papers, as found by Europe PMC text mining. Sharing a sentence is not in itself a finding about the gene and the disease. The quoted sentences say what the papers report.
deafness (1 paper, 2023). An inherited or acquired condition characterized by the complete loss of the ability to hear from one or both ears. "Human ANKEF1, ODF3L2, and SAXO2 chromosomal locations compared to potentially associated deafness loci." (PMID 37367482, 2023). "The Shared Harvard Inner Ear Database (SHIELD) reports that human ODF3L2 and SAXO2 lie within deafness loci DFNB72 and DFNA30, respectively." (PMID 37367482, 2023). "Human SAXO2 (also known as FAM154B) and ODF3L2 are reported in SHIELD as mapping to deafness loci DFNA30 and DFNB72, respectively." (PMID 37367482, 2023). "Although it is still possible that ODF3L2 and SAXO2 contribute to auditory or vestibular function, we propose that they should be excluded as candidates for the currently known deafness loci." (PMID 37367482, 2023). "However, neither SAXO2 nor ODF3L2 resides within any known deafness loci, based on our analysis of the genetic markers used to map these and other nearby loci." (PMID 37367482, 2023).
sensorineural deafness (1 paper, 2023). "Human SAXO2 is located on 15q25.2 near several sensorineural deafness loci, including DFNA30 (gene unknown), DFNA68 (HOMER), DFNB48 (CIB2), and OTSC1." (PMID 37367482, 2023).
SAXO2 also shares sentences with these, for which no sentence is quoted: glaucoma (1 paper).